G6PD (glucose-6-phosphate dehydrogenase)
Diseases named in the same sentence as G6PD in open-access papers (continued):
Sharing a sentence is not in itself a finding about the gene and the disease.
cervical carcinoma (continued). "Taken together, these results indicate that miR-1 might suppress the development and progression of HR-HPV-16/18+ cervical cancer by directly targeting G6PD, and that miR-1 might therefore be a valuable novel therapeutic candidate." (PMID 27861141, 2016). "In order to explore whether HPV E6 takes part in the carcinogenic progress of cervical cancer by regulating G6PD, the G6PD expressional upregulation (plenti G6PD) or downregulation (G6PD siRNA) were conducted in HeLa cells on the basis of the HPV16 E6 siRNA and/or overexpressing, respectively." (PMID 34692493, 2021). "Highly expressed DCBLD1 can impede the autophagic degradation of glucose-6-phosphate dehydrogenase (G6PD), thereby activating the pentose phosphate pathway (PPP) and promoting the progression and metastasis of cervical cancer." (PMID 40399304, 2025). "This upregulation enhanced the expression and enzyme activity of glucose-6-phosphate dehydrogenase (G6PD), which stimulated the pentose phosphate pathway (PPP), promoting the proliferation and metastasis of cervical cancer cells." (PMID 39925738, 2025). "This modification stabilizes DCBLD1 expression, leading to an increase in the expression and enzymatic activity of glucose-6-phosphate dehydrogenase (G6PD), which stimulates the PPP and promotes the progression of cervical cancer." (PMID 40584966, 2025). "In HPV-related cervical cancer, the HPV16 E6E7 protein inhibits lactylation of G6PD at the K45 site, promoting G6PD dimerization and enhancing its activity." (PMID 39979245, 2025). "DCBLD1 overexpression inhibited G6PD autophagic degradation, activating PPP to promote cervical cancer progression." (PMID 38291438, 2024). "In human cervical cancer tissues and xenograft tumor samples, DCBLD1 positively correlated with G6PD." (PMID 38291438, 2024). "We identified G6PD-mediated oxiPPP as a crucial proliferative-related target of DCBLD1, establishing a link between DCBLD1 and the altered oxiPPP in cervical cancer." (PMID 38291438, 2024). "This event serves to upregulate the enzymatic activity of G6PD, thereby activating the pentose phosphate pathway (PPP), which, in turn, fosters the proliferation of cervical cancer cells." (PMID 39867891, 2024). "In HR-HPV-positive cervical cancer cells, miR-206 targets the 3′-UTR of G6PD mRNA and blocks its expression as well." (PMID 35207558, 2022). "Furthermore, the correlation between changes in HPV16 E6 expression and the corresponding alteration in G6PD expression led us to hypothesize that HPV16 E6 contributes to the tumorigenesis and progression of cervical cancer by regulating the expression of host G6PD." (PMID 34692493, 2021). "By reducing G6PD expression, miR-1 inhibited proliferation and promoted apoptosis in HR-HPV+ cervical cancer cells, and reduced the growth of tumor xenografts in nude mice." (PMID 27861141, 2016). "Our research found that the expression levels of E6 protein and G6PD in cervical cancer were significantly increased compared with the non-cancer cohort." (PMID 34692493, 2021). "Furthermore, G6PD expression is elevated in many kinds of tumors, including endometrial carcinomas and HR-HPV+ cervical cancer." (PMID 27861141, 2016). "The detection of G6PD enzyme activity is consistent with the protein expression level, suggesting that FRA1 can inhibit the PPP bypass of cervical cancer cells, while LPS can negatively regulate the inhibition of FRA1 and restore the PPP bypass level of cervical cancer cells." (PMID 33456361, 2021). "Furthermore, by regulating the expression of G6PD, HPV16 E6 might promote the proliferation and migration potential, and inhibit apoptosis of cervical cancer cells, which ultimately contributed to the progression and metastasis of cervical cancer." (PMID 34692493, 2021).
deficiencies (26 papers, 2008 to 2025). "We measured G6PD activity in 114,285 neonates born in the Heze area and identified 80 patients with G6PD deficiencies." (PMID 40313950, 2025). "Deficiency of glucose-6-phosphate dehydrogenase (G6PD) is a common inherited red blood cell enzyme deficiency caused by mutations in G6PD, which has an X-linked incompletely dominant inheritance and can cause hemolytic anemia." (PMID 40313950, 2025). "In Southeast Asia, the predominant allele is Mahidol, which explains 38–96% in of G6PD deficiencies in Burma, Thailand and Myanmar." (PMID 34652573, 2022). "In India, in various population groups, it was discovered that 8.5% of people have G6PD deficiencies." (PMID 36704359, 2022). "G6PD deficiencies were most frequent in Africa, the Middle East and Southeast Asia with pronounced differences in variant composition." (PMID 34652573, 2022). "Glucose-6-phosphate dehydrogenase (G6PD) deficiency is one of the most common clinically significant enzymopathies and affects 400 million persons worldwide." (PMID 36353116, 2022). "Glucose-6-phosphate dehydrogenase (G6PD) deficiency is one of the most common enzymatic disorders of red blood cells, with a particularly high prevalence in tropical and subtropical regions, including southern China." (PMID 36704359, 2022). "While it also constitutes a relevant factor in India, explaining around 24% of G6PD deficiencies in a country-wide survey, the overall most prevalent allele was Orissa, which accounted for 57% of all deficiencies." (PMID 34652573, 2022). "Second, 8-amoniquinolines can cause haemolysis in patients with Glucose 6 Phosphate Dehydrogenase deficiencies (G6PDd)." (PMID 33757538, 2021). "While extensive studies have been done throughout Southeast Asia to examine the prevalence and diversity of G6PD deficiencies, studies reporting data from Africa are emerging and limited." (PMID 34699526, 2021). "Glucose-6-phosphate dehydrogenase (G6PD) deficiency is an X-linked, recessive condition that causes intermittent jaundice or hemolytic anemia because of low NADPH levels in red blood cells." (PMID 34532700, 2021). "The key findings in our study demonstrate that G6PD deficiency plays an essential role in the initiation of a cardiovascular disease event via the TGF-β/NADPH oxidases/ROS signaling pathway." (PMID 33050491, 2020). "Glucose-6-phosphate dehydrogenase (G6PD) deficiency, the most common genetic inherited trait among humans, affects ~7% of the global population, and is associated with excess risk of cardiovascular disease (CVD)." (PMID 33050491, 2020). "Previously it was shown that TGF-β/Smad signaling upregulates several NOX enzymes and also G6PD deficiency activates monocytes and alters macrophage polarization." (PMID 33050491, 2020). "Future studies are needed to elucidate the role of G6PD deficiency in EndMT and myocardial fibrosis." (PMID 33050491, 2020). "Males are either G6PD deficient or normal, but females exhibit a broader range of G6PD deficiencies, from severe deficiency to normal." (PMID 33050491, 2020). "Progress in the development of a new P. vivax antimalarial drug, tafenoquine, has driven the development of simple and reliable quantitative tests for G6PD deficiency." (PMID 30184203, 2019). "Statiscally significant differences p=0.036 and p=0.038 were established between the Hb concentration of the participants having a G6PD deficiency and those with normal G6PD activity for males and females, respectively." (PMID 31016042, 2019). "Women heterozygous for G6PD deficiency with intermediate activity levels are approximately twice as prevalent in a population than homozygous G6PD-deficient females and hemizygous G6PD-deficient males." (PMID 30184203, 2019). "Deficiency of glucose-6-phosphate dehydrogenase (G6PD) is an X-linked hereditary genetic defect that is the most common polymorphism and enzymopathy in humans." (PMID 27053284, 2016).
deficiencies (continued). "Hereditary non-spherocytic hemolytic anemias (HNSHA) are a heterogeneous group of RBC enzymatic disorders with PK and G6PD deficiencies being the most common lesions." (PMID 22509282, 2012). "The antimalarial primaquine is among the agents that may trigger hemolysis among G6PD-deficient people, and primaquine-sensitive erythrocytes were crucial in demonstrating the pathophysiology of the G6PD deficiencies." (PMID 36191877, 2022). "G6PD-type A− deficiency accounts for 90% of all G6PD deficiencies in tropical Africa." (PMID 35035485, 2022). "Additionally, the performance of first-generation qualitative CareStart G6PD rapid diagnostic tests (RDT) were evaluated for the screening of G6PD deficiency in point-of-care (POC) settings." (PMID 34699526, 2021). "In tropical Africa, the G6PD type A− variant accounts for 90% of all G6PD deficiencies." (PMID 34577605, 2021). "G6PD deficiency diagnosis can be made in women homozygous for G6PD gene mutations." (PMID 34200975, 2021). "The foremost aim of this study was to evaluate the effect of G6PD deficiency (to mimic G6PD A− variant; mild-moderate) on TGF-β/NADPH oxidases/ROS signaling and cell adhesion molecules (CAM) in human aortic endothelial cells (HAEC) and monocyte-endothelial adhesion." (PMID 33050491, 2020). "Glucose-6-phosphate dehyrdgoenase (G6PD) deficiency is a common X-linked genetic trait, with an associated enzyme phenotype, whereby males are either G6PD deficient or normal, but females exhibit a broader range of G6PD deficiencies, ranging from severe deficiency to normal." (PMID 30184203, 2019). "Importantly, use of antimalarials is problematic because the hemolytic anemia observed in individuals with G6PD deficiencies is variable." (PMID 27053284, 2016). "This might represent the evolution of balanced polymorphisms, maintained by natural selection through heterozygote advantage or spatial-temporal selection of alternative alleles, as it has been shown for G6PD deficiencies or phenylketonuria." (PMID 18304320, 2008). "About 40% of the population exposed to the risk of P. vivax infection in southeast Asia, where relevant data are available, is not eligible for the standard anti-relapse treatment with primaquine due to G6PD deficiency and may face treatment failure due to poor drug metabolism." (PMID 41452897, 2025). "Similarly, data on G6PD deficiencies and comorbidities in the control group were also unavailable." (PMID 40990168, 2025). "However, the detection rate of the c.487G>A mutation in the Heze area was greater than that of c.1376G>T, ranking second, suggesting that difference in population and economic and cultural development have altered the genetic mutation types of G6PD deficiencies in the Heze area." (PMID 40313950, 2025). "Of the remaining 76 (17.6%) white Moors, 8 (10.5%) were Duffy-negative and affected with G6PD A– type deficiency, mostly in heterozygous females (n = 6)." (PMID 41452897, 2025). "Based on the level of residual enzyme activity, the World Health Organization (WHO) has categorized G6PD deficiencies into five classes: I (<10% of normal, chronic nonspherocytic hemolytic anemia); II (<10% of normal); III (10–60% of normal); IV (60–150% of normal), and V (>150% of normal)." (PMID 36353116, 2022). "Routine evaluation of samples began with non-proteomic approaches including testing for unstable hemoglobin and evaluation of enzymatic activity for the most common causes of HNSHA (G6PD, PK, and Hexokinase deficiency), if not previously reported in the patient’s record." (PMID 22509282, 2012).
gastric cancer (23 papers, 2015 to 2025). A primary or metastatic malignant neoplasm involving the stomach. "This study aimed to evaluate the potential of glucose-6-phosphate dehydrogenase activity, which is a factor associated with cancer progression, as a biomarker for predicting the stage of gastric cancer." (PMID 41374996, 2025). "Firstly, this study is the first to investigate and establish the diagnostic performance and cutoff point of serum G6PD activity as a potential biomarker for gastric cancer." (PMID 41374996, 2025). "The protein abundance of PFKFB3 and G6PD was increased in gastric cancer tissues, which was associated with increased TNM stage." (PMID 31591390, 2019). "Therefore, while our study provides preliminary evidence supporting the association between serum G6PD levels and gastric cancer stage, additional studies are required to establish clinical utility of serum G6PD test." (PMID 41374996, 2025). "In addition, another previous study reported that G6PD overexpression in gastric cancer tissues was associated with the TNM stage and the presence of distant metastasis." (PMID 41374996, 2025). "However, biomarkers that have been evaluated for their diagnostic performance in predicting gastric cancer stage are scarce, highlighting the advantage of serum G6PD levels as a potential tool to screen for disease progression in gastric cancer patients." (PMID 41374996, 2025). "Youden’s index was applied to identify the optimal cutoff point of G6PD activity that best discriminates between early-stage and advanced-stage gastric cancer." (PMID 41374996, 2025). "Specifically, LINC00242 is highly expressed in gastric cancer tissues and cells and positively correlates with G6PD expression." (PMID 41220952, 2025). "G6PD activity was significantly higher in the advanced-stage group compared to early-stage group and served as a predictive factor for gastric cancer stage." (PMID 41374996, 2025). "The findings of this study highlight the potential clinical utility of G6PD activity as a biomarker for distinguishing between early-stage and advanced-stage gastric cancer." (PMID 41374996, 2025). "This study highlighted the potential clinical value of serum G6PD activity as an indicator for assessing gastric cancer stage." (PMID 41374996, 2025). "In the multivariable logistic regression model adjusting for age and gender, G6PD activity remained an independent predictor of advanced-stage gastric cancer (OR 5.62, 95% CI 1.41–22.38)." (PMID 41374996, 2025). "G6PD is highly expressed and activates the NF-κB signaling pathway, thereby promoting the production of hepatocyte growth factor (HGF) in gastric cancer-associated mesenchymal stem cells (GCMSCs)." (PMID 39859324, 2025). "This study aimed to evaluate the potential of glucose-6-phosphate dehydrogenase activity as a biomarker for predicting the stage of gastric cancer." (PMID 41374996, 2025). "This study provides clinical evidence supporting the use of serum G6PD activity to distinguish between early-stage and advanced-stage gastric cancer." (PMID 41374996, 2025). "In summary, these results indicate that RORα plays a crucial role in gastric cancer proliferation and glycolysis by modulating G6PD and PFKFB3 genes." (PMID 38184549, 2024). "Overexpression of LINC00242 in gastric cancer cells inhibits miR-1-3p expression, which in turn adversely regulates G6PD expression." (PMID 38191389, 2024). "In summary, our study demonstrates that RORα inhibits gastric cancer proliferation by attenuating the glycolytic ability induced by G6PD and PFKFB3 in GC." (PMID 38184549, 2024). "In our study, we demonstrated that the upregulation of CARM1 in gastric cancer promotes glucose influx toward the PPP under metabolic stress by regulating the gatekeeper enzyme G6PD." (PMID 39266534, 2024). "The upregulation of G6PD in gastric cancer activates NF-κB signaling to promote cancer cell metastasis." (PMID 35711939, 2022).
gastric cancer (continued). "In the study, we analyzed datasets from Gene Expression Omnibus (GEO) to identify mRNAs regulated aerobic glycolysis in gastric cancer, and G6PD was selected." (PMID 33514309, 2021). "Linear correlation was adopted to ascertain the relationship between miR-1-3p expression and G6PD expression in 77 gastric cancer tissue samples." (PMID 33514309, 2021). "LINC00242, miR-1-3p and G6PD expression levels in gastric cancer tissues and cells were determined by qRT-PCR." (PMID 33514309, 2021). "These outcomes concluded that overexpression of miR-1-3p restrained gastric cancer cell proliferation and glycolysis, possibly in a G6PD-related way." (PMID 33514309, 2021). "In the current research, for the first time, we found that the G6PD is a key regulator of Warburg effect and paly the oncogenic role within gastric cancer." (PMID 33514309, 2021). "In summary, sufficient evidences were provided to feature the latent molecular mechanism of G6PD in gastric cancer aerobic glycolysis." (PMID 33514309, 2021). "LINC00242 exhibited a negative correlation with miR-1-3p in 77 gastric cancer tissues (R = − 0.4565, P < 0.0001); LINC00242 and G6PD appeared a positive relevance with each other in 77 gastric cancer tissues (R = 0.3300, P = 0.0034)." (PMID 33514309, 2021). "The biological function of G6PD to gastric cancer in the research was investigated in gastric cancer cells in vitro and xenograft mice in vivo." (PMID 33514309, 2021). "Mouse tumor xenograft model was employed to investigate the impacts of G6PD on gastric cancer in vivo." (PMID 33514309, 2021). "LINC00242 plays a stimulative role in gastric cancer aerobic glycolysis via regulation of miR-1-3p/ G6PD axis, therefore affecting gastric cancer cell proliferation." (PMID 33514309, 2021). "All these outcomes uncovered that G6PD is closely related to the progression of gastric cancer by promoting the aerobic glycolysis." (PMID 33514309, 2021). "There is only one mRNA (G6PD) both highly expressed in gastric cancer tissue samples of GSE51575, GSE63089 and GSE81948 microarray." (PMID 33514309, 2021). "We found that LINC00242 impose effects by sponging miR-1-3p expression, which negatively regulate G6PD expression, to affect gastric cancer cell proliferation and aerobic glycolysis." (PMID 33514309, 2021). "Based on ENCORI database, the expression levels of miR-1-3p and G6PD was observably negatively correlated in gastric cancer (R = − 0.166, P = 0.00134)." (PMID 33514309, 2021). "Knockdown of G6PD restrained gastric cancer cell proliferation and glycolysis in vitro and relieves the tumorigenesis of gastric cancer in vivo." (PMID 33514309, 2021). "These consequences disclosed that miR-1-3p targeted G6PD and regulated G6PD expression in gastric cancer." (PMID 33514309, 2021). "Considering that there are many lncRNAs and miRNAs deregulated in gastric cancer, the research purposed to ascertain a novel lncRNA-miRNA axis regulating G6PD expression and Warburg effect in gastric cancer." (PMID 33514309, 2021). "Then, this study investigated the G6PD expression levels was observably up-regulated in gastric cancer tissue samples based on online datasets GSE29272 and GSE63089." (PMID 33514309, 2021). "And the biological functions of G6PD in gastric cancer cell proliferation, apoptosis, aerobic glycolysis progression and tumor formation were determined in vitro and in vivo." (PMID 33514309, 2021). "The finding of LINC00242/miR-1-3p/G6PD axis in gastric cancer facilitated us to better understand the development of gastric cancer, thus provided new therapeutic strategies for this fatal disease." (PMID 33514309, 2021). "The G6PD mRNA expression level in 77 gastric cancer tissue samples was dramatically increased when compared with that corresponding adjacent normal tissue samples (P < 0.01)." (PMID 33514309, 2021).